SLC7A11 (solute carrier family 7 member 11)
Diseases named in the same sentence as SLC7A11 in open-access papers (continued):
Sharing a sentence is not in itself a finding about the gene and the disease.
lung cancer (continued). "The high expression of SLC7A11 is accompanied by the high proliferation capacity and high invasion ability of lung cancer cells, which in turn is related to the cell ferroptosis involved in SLC7A11." (PMID 35399708, 2022). "Taken together, our results uncovered a Uc.339/miR-339/SLC7A11 axis that leads to defects in the ferroptosis in lung cancer, and constitutes a potential mechanism that drives the metastasis of lung adenocarcinoma." (PMID 35399708, 2022). "Taken together, these data suggested that UC.339 can promote lung cancer metastasis in vivo through the Uc.339/miR-339/SLC7A11 axis." (PMID 35399708, 2022). "The results of in vitro data suggested a potential role for Uc.339/miR-339/SLC7A11 axis in enhancing lung cancer cell metastasis." (PMID 35399708, 2022). "Meanwhile, our recent study revealed that RBMS1 regulates lung cancer ferroptosis through translational control of SLC7A11." (PMID 35538152, 2022). "The stem cell factor SOX2 can inhibit ferroptosis in lung cancer stem-like cells via upregulating SLC7A11 expression." (PMID 36266731, 2022). "SLC7A11 is overexpressed in many types of cancers including lung cancer and triple-negative breast cancer." (PMID 35053507, 2022). "Downregulation of solute carrier 7A11 (SLC7A11) expression in lung cancer inhibits cell proliferation and colony formation." (PMID 36553648, 2022). "SLC7A11 is highly expressed in lung cancer and is regulated by both transcriptional and translational pathways." (PMID 35882850, 2022). "To more intuitively explore the influence of Uc.339/miR-339/SLC7A11 axis on the metastasis of lung cancer, we used a CCK-8 kit to evaluate the level of cell proliferation." (PMID 35399708, 2022). "At the post-transcriptional level, SLC7A11 is stabilized by OTU deubiquitinase via ubiquitin aldehyde binding 1 (OTUB1)-mediated deubiquitination in H1299 lung cancer cells." (PMID 34742351, 2021). "SLC7A11 was reported to confer resistance to ferroptosis in cancer cells and is adaptively expressed to reduce ferroptosis and buffer irradiation damages in lung cancer cells." (PMID 34531924, 2021). "Our results showed that both SLC7A11 and GPX4 were overexpressed in colorectal cancer, and SLC7A11 was overexpressed in lung cancer." (PMID 34722530, 2021). "Up to now, various studies have pointed to the role of this system in the regulation of ferroptosis in lung cancer, most of them representing SLC7A11 as the targets of various novel drugs and upstream regulators." (PMID 34926310, 2021). "KEAP1 is frequently mutated in lung cancer, and KEAP1-mutant lung cancer exhibits NRF2 hyperactivation and aberrant expression of SLC7A11." (PMID 33000412, 2021). "Consistent with this, SLC7A11 is overexpressed in multiple cancer types, including lung cancer, TNBC, PDAC, renal cell carcinoma, liver cancer, and glioma, and its high expression often correlates with poor prognosis." (PMID 33000412, 2021). "Regardless, multiple evidence support SLC7A11 as a therapeutic target since it can promote lung cancer progression in vitro and in vivo." (PMID 34742351, 2021). "Inhibition of SLC7A11 by sulforaphane or YTHDC2 (a m6A reader) induced the ferroptosis of lung cancer cells and suppressed the progression of lung cancer." (PMID 34722530, 2021). "Overexpressing SLC7A11 promotes radioresistance in lung cancer cells through inhibiting irradiation-induced ferroptosis." (PMID 34531924, 2021). "The upregulated genes included CYP4F3, IL1RL1, PTGS2, and CXCL8, which are related to inflammation; HKDC1, MYEF2 and CYP1A1, which are related to hepatocarcinoma or lung carcinoma; and SLC7A11 and NEFM, which are related to neuronal damage." (PMID 33247188, 2020).
lung cancer (continued). "Experimental validation confirmed the unique over-expression of predicted surface markers (MUC4, MSLN, and SLC7A11) in lung cancer cells at the protein level." (PMID 29560830, 2018). "In addition, activation of the YAP protein has been shown to upregulate the expression of SLC7A11, thus inhibiting ferroptosis in non–small cell lung cancer." (PMID 40962058, 2025). "Moreover, the use of BEVs expressing SLC7A11 siRNA presents a novel strategy for targeted gene silencing in lung cancer therapy, promoting ferroptosis as a mechanism to inhibit tumor progression." (PMID 41030277, 2025). "Furthermore, SLC7A11 expression is also directly stimulated by the stem cell transcription factor SOX2 in lung cancer stem-like cells (CSLCs)." (PMID 39875356, 2025). "By diminishing the migratory and invasive capacities of NSCLC cells, SLC7A11 knockdown could serve as a promising strategy to combat metastasis, which often complicates treatment outcomes in lung cancer patients." (PMID 41030277, 2025). "Consequently, this resulted in increased sensitivity to ferroptosis, further implicating SLC7A11 as a pivotal regulator of redox homeostasis in lung cancer." (PMID 41030277, 2025). "SLC7A11 expression was significantly associated with poorer overall survival in lung cancer but showed no prognostic relevance in ovarian cancer." (PMID 40784667, 2025). "Similarly, high expression of SLC7A11 is considered a marker of poor prognosis in lung cancer patients." (PMID 39917300, 2025). "Interestingly, Wang and colleagues previously reported that loss of H2Bub1 by RNF20 KD results in increased ferroptosis in lung cancer cells by downregulating SLC7A11." (PMID 40597205, 2025). "In addition, elevated RBMS1 was observed in lung cancer patients, and RBMS1 deficiency inhibited the translation of SLC7A11 and promoted ferroptosis through the translation initiation factor eIF3d." (PMID 41214391, 2025). "SOX also upregulated SLC7A11 expression, conferring resistance to ferroptosis in lung cancer." (PMID 39518098, 2024). "Alterations in SLC7A11 gene expression may also sensitize HPV-positive lung cancer to certain chemotherapy drugs, such as cisplatin." (PMID 39769017, 2024). "Additionally, the ubiquitin-specific protease 35 can modulate ferroptosis in lung cancer by targeting iron transport protein.The ubiquitination regulation extends to SLC7A11 as well." (PMID 38515565, 2024). "Interestingly, curcumin induced a decrease in SLC7A11 levels in tumor tissues from homozygous Lewis lung carcinoma mice, and this phenomenon was similarly observed in several lung cancer cells." (PMID 39309443, 2024). "For example, RBMS1 regulated lung cancer ferroptosis through translational control of SLC7A11." (PMID 38605214, 2024). "The knockdown of PRIM2 enhanced the sensitivity of NCI-H23 cells to dihydroartemisinin therapy, while the overexpression of PRIM2 had the opposite effect, indicating that dihydroartemisinin induced ferroptosis in lung cancer cells by upregulating the PRIM2/SLC7A11 pathway." (PMID 39202965, 2024). "Importantly, targeting SLC7A11 using its inhibitor, erastin, showed obvious inhibition on the colony formation of lung cancer cells and cancer development with ELF3 overexpression and PTEN deficiency by inducing ferroptosis." (PMID 39695109, 2024). "Many natural products that target SLC7A11 in lung cancer have been discovered." (PMID 39104501, 2024). "All of these results suggest that high expression of SLC7A11 inhibits the ferroptosis levels of lung cancer cells, leading to accelerated proliferation and migration, which may be associated with poor prognosis." (PMID 38655266, 2024). "STAT1's function is similar to STAT3, affecting SLC7A11 expression in lung cancer." (PMID 39104501, 2024).
lung cancer (continued). "Through a significance analysis of microarrays (SAM) analysis, we found that the solute carrier family 7-member 11 (SLC7A11/xCT) gene (an antiporter that mediates the uptake of extracellular cystine) is up-regulated in tobacco-smoke- and HPV-associated lung cancers." (PMID 39769017, 2024). "Moreover, the expression level of SLC7A11 was negatively correlated to the survival of lung cancer patients with low expression levels of PTEN in lung tumors." (PMID 39695109, 2024). "The expression of xCT (SLC7A11) is notably increased in TAMs of lung cancer, demonstrating that xCT may have a function in regulating the TME of lung cancer." (PMID 39802954, 2024). "Additionally, lung cancer cells defective in Keap1 are glucose dependent; when glucose levels are low, high uptake of cystine by lung cancer cells via the Nrf2/SLC7A11 axis stimulates the accumulation of intracellular disulfide bonds and depletion of NADPH." (PMID 39557840, 2024). "SOX2 also activates SLC7A11 in lung cancer cells, enhancing their cysteine uptake." (PMID 39744129, 2024). "Thus, SLC7A11 can protect cancer cells from cisplatin by absorbing cystine for cysteine production during lung cancer treatment." (PMID 39769017, 2024). "It has been elucidated that there may be some association between the expression of SLC7A11 and SLC3A2, CD8+T cell count, IFN-γ expression and the prognosis of lung cancer patients." (PMID 38515565, 2024). "Additionally, the SLC7A11 gene expression levels correlate with HPV16 E6/E7 overexpression in lung cancer cells." (PMID 39769017, 2024). "Thus, this study suggests that SLC7A11 up-regulation is associated with both HPV-positive and tobacco-smoke-associated lung carcinomas, with a potential association with clinical prognosis." (PMID 39769017, 2024). "Therefore, it is very beneficial to find more upstream targets of SLC7A11 regulation to promote ferroptosis of lung cancer." (PMID 37005430, 2023). "XAV-939, a Tankyrase inhibitor, has been shown to promote ferroptosis in lung cancer cells by inducing the down-regulation of SLC7A11, and inhibiting the progression of lung cancer by down-regulating lncRNA MIR503HG, sponging miR-1273c and regulating SOX4 expression." (PMID 37005430, 2023). "The research based on the inhibition of ferroptosis by the antioxidant enzyme SLC7A11/GPX4 axis may be a breakthrough in the treatment of lung cancer." (PMID 37266741, 2023). "Overall, AhR may regulate iron, GSH, and lipid ROS levels in lung cancer cells by promoting SLC7A11 transcription, thereby inhibiting lung cancer cell ferroptosis and promoting non-small cell lung cancer development." (PMID 37056388, 2023). "SLC7A11 controlled the development of lung cancer via ferroptosis." (PMID 35997855, 2023). "Furthermore, we need to find out how the Uc.339/miR-339/SLC7A11 axis affects the metastasis of lung cancer." (PMID 35399708, 2022). "Moreover, SLC7A11 is also upregulated in lung cancer stem cell-like cells and activated by the cell transcription factor SOX2." (PMID 36105219, 2022). "KRAS mutant lung cancer cells are vulnerable to the ferroptosis induced by SLC7A11 inhibition." (PMID 35805124, 2022). "Therefore, we first detected various ferroptosis-related genes to further understand the influence of Uc.339/miR-339/SLC7A11 axis on the development of lung cancer and its mechanism." (PMID 35399708, 2022). "DHA induces lung cancer cell ferroptosis via the inactivation of the PRIM2/SLC7A11 axis." (PMID 35805124, 2022). "Conversely, SLC7A11 overexpression enhances the resistance of lung cancer cells to cisplatin." (PMID 36105219, 2022). "Recent research suggests that cancer therapies, such as immunotherapy and radiotherapy, can induce ferroptosis partly through modulating SLC7A11 expression; knockout or inhibition of SLC7A11 has a significant inhibitory effect on lung cancer and pancreatic cancer cells." (PMID 35517862, 2022).
lung cancer (continued). "We next extracted samples of 506 lung cancer patients in the TCGA database, and the analysis showed that the mRNA expression level of miR-339 in lung adenocarcinoma was highly negatively correlated with SLC7A11." (PMID 35399708, 2022). "SLC7A11 is overexpressed in various malignant tumors and is closely related to the growth, prognosis, metastasis, and treatment of malignant tumors including breast, ovarian, liver, and lung cancers." (PMID 36160450, 2022). "In addition, RBMS1, directly interacting with translation initiation factor eIF3d, promotes lung cancer progression through translational regulating SLC7A11." (PMID 35882850, 2022). "KEAP1-mutant lung cancers are characterized by high SLC7A11 expression levels." (PMID 35280777, 2022). "Likewise, deficiency of the tumor suppressor KEAP1 (which is frequently mutated in lung cancer) inhibited IR-induced ferroptosis at least partly through stabilizing NRF2 and upregulating SLC7A11, leading to radioresistance." (PMID 33891303, 2021). "The expression of SLC7A11 was significantly higher in melanoma and lung cancer patients." (PMID 33935284, 2021). "Moreover, KRAS mutant lung cancer cells are sensitive to ferroptosis induced by the inhibition of SLC7A11." (PMID 34742351, 2021). "In addition, DHA impedes colony formation, proliferation and induction of ferry death in lung cancer cells by blocking the PRIM2/SLC7A11 axis." (PMID 34539408, 2021). "In tissues of nonsmall cell lung cancer, the Slc7a11 expression was higher." (PMID 32587657, 2020). "PFKP and SLC7A11 have been reported to regulate the metabolic levels of lung cancer cells." (PMID 33042838, 2020). "While accumulating evidence shows that SLC7A11 is precisely regulated at both transcriptional and post-translational levels, the specific transcription, post-transcription, and post-transcriptional modifications of SLC7A11 in lung cancer remain unclear." (PMID 40861466, 2025). "YEATS4 amplification samples show increased mRNA levels of several well-known antioxidant genes, including NQO1, SLC7A11, and GCLC, suggesting beside NFE2L2 mutation and KEAP1 mutation, YEATS4 amplification could be the other critical genetic marker in lung cancer by modulating antioxidant pathways." (PMID 38514704, 2024). "Thus, we selected SLC7A11 for subsequent analysis in lung carcinomas." (PMID 39769017, 2024). "Thus, it can be speculated that SLC7A11 overexpression in both HPV-positive and tobacco-smoke-associated lung carcinomas is mediated by the activation of the MAPK, PI3K, or NF-κB pathways." (PMID 39769017, 2024). "Moreover, posttranslational regulation of SLC7A11 by RBMS1 mediates ferroptosis in lung cancer." (PMID 37210575, 2023). "Moreover, it was reported that SOX2 confers resistance to ferroptosis through upregulation of SLC7A11 expression in lung cancer stem-like cells (CSLC) which implies that SOX2 could be a potential therapeutic target for cancer treatment." (PMID 36926345, 2023). "In addition to SLC7A11, lung cancer cell also exhibits high GPX4 expression." (PMID 36105219, 2022). "However, a lot of studies have reported that the inhibition of ferroptosis is ubiquitous in lung cancer cells; for example, xCT (SLC7A11), serine/threonine/tyrosine kinase 1 (STYK1), and iron–sulfur cluster biosynthetic enzyme (NFS-1) have been found to be highly expressed in NSCLC cells." (PMID 35875069, 2022). "Some preclinical studies show that DNA primase subunit 2 (PRIM2) is a negative regulator of DHA-induced ferroptosis in lung cancer cells (NCI-H23) through sustaining SLC7A11 expression, indicating that PRIM2 may plays a DNA primase-independent role in shaping ferroptosis." (PMID 34742351, 2021). "In addition, POU2F1 showed the highest expression levels in the lungs, which may be related to the expression and important roles of SLC7A11 in response to lung cancer." (PMID 32443864, 2020).
lung cancer (continued). "In lung cancer, for instance, SOX2 can activate SLC7A11 expression, enhancing resistance to ferroptosis and increasing tumor aggressiveness and drug resistance." (PMID 41330917, 2025). "In lung cancer, the RNA-binding protein RBMS1 augmenting the expression of SLC7A11 leads to an elevation in the production of GSH and consequently suppresses ferroptosis." (PMID 40765833, 2025). "SLC7A11 and AIFM2 expression correlated with GPX4 inhibitors’ AUC (i.e., resistance to RSL3, ML162, and ML210) in lung cancer CLs, in agreement with the previously reported correlation in non-hematopoietic CLs in general." (PMID 39995872, 2025). "Mechanistically, Huaier simultaneously and independently downregulates the antioxidant pathway SLC7A11/GPX4 and elevates intracellular iron levels through NCOA4-mediated ferritinophagy degradation of FTH1 in lung cancer cells." (PMID 40623982, 2025). "In lung cancer cells, METTL3 can simultaneously regulate the mRNA stability of TFR1 and SLC7A11, which in turn decreases cellular vulnerability to ferroptosis." (PMID 39875356, 2025). "In lung cancer, DHA inhibits proliferation and colony formation, increases cell death, and induces ferroptosis in lung cancer cells by inactivating the PRIM2/SLC7A11 axis." (PMID 40994946, 2025). "Zerumbone is a naturally occurring compound derived from ginger rhizome, which can be used in combination with thyrosine kinase inhibitors like gefitinib for treatment of lung cancer, acting by inducing ferroptosis and inhibiting Akt/STAT3/SLC7A11 axis." (PMID 39104501, 2024). "SLC7A11 is under the control of many oncogenes (e.g., MiR-27a-3p, RBMS1, SOX2) in lung cancer, leading to its overactivity and ferroptosis induction resistance." (PMID 39104501, 2024). "In human lung cancer tissues, the overexpression of SOX2 and SF3B1 enhances cell resistance to ferroptosis and correlates positively with SLC7A11 expression." (PMID 39624080, 2024). "Cancer cells exhibiting elevated levels of SLC7A11 expression demonstrate a reliance on glucose metabolism, while cells with reduced SLC7A11 expression show heightened oxidative phosphorylation (OXPHOS) activity, as observed in lung cancer cell lines." (PMID 39040097, 2024). "The role of AHR and NRF2 in regulating ferroptosis in breast and lung cancer cells is unclear, but AHR has been shown to promote the development of non-small cell lung cancer (NSCLC) by inducing the expression of SLC7A11, a key regulator of ferroptosis." (PMID 38982523, 2024). "SLC7A11 expression increased in response to stimulation with the transcription factor SOX2, rendering lung cancer cells more resistant to upper iron." (PMID 38562175, 2024). "Research indicates that RBMS1, as a translation regulator for ferroptosis, promotes the translation of SLC7A11 through its T3 region in the 3′-UTR, leading to an escape from ferroptosis and furthering lung cancer progression." (PMID 38515565, 2024). "Finally, the effect of EC on ferroptosis in lung cancer cells was tested, and the results revealed that EC treatment significantly increased the Fe2+ concentrations in H460 and H1299 cells while inhibiting the expression of the ferroptosis-related proteins SLC7A11, GPX4, and FTH1." (PMID 39480832, 2024). "In lung cancer stem-like cells, SRY (sex determining region Y)-box 2 (SOX2) binds to the SLC7A11 promoter to increase its expression, conferring ferroptosis resistance and promoting stemness." (PMID 38705513, 2024). "The impaired BRD4 downregulates GPX4, SLC7A11, and SLC3A2 expression in breast and lung cancer cell lines and promotes ferroptosis." (PMID 38392340, 2024). "SLC7A11 can be activated by the transcriptional factor SRY-box transcription factor 2 (SOX2) and the splicing factor 3b subunit 1 (SF3B1) in lung cancer cells." (PMID 39624080, 2024). "Curcumin promotes ferroptosis, thereby inhibiting lung cancer tumor growth, by upregulating ACSL4 and downregulating ferroptosis-inhibiting genes (SLC7A11 and GPX4)." (PMID 38892270, 2024).